PSG4 (pregnancy specific beta-1-glycoprotein 4)
Synonyms: PSBG-4
Tractability: Antibody: UniProt places it where antibodies can reach, with high confidence; UniProt predicts a signal peptide or a membrane-spanning region; its Gene Ontology location is reachable by antibodies, with medium confidence.
Gene: Protein-coding gene on chromosome 19 (43,192,702 to 43,207,299, reverse strand). Ensembl gene ENSG00000243137.
Subcellular location: Secreted
Pathways (Reactome):
Hemostasis: Cell surface interactions at the vascular wall
Gene Ontology:
Biological process: female pregnancy
Cellular component: extracellular region
Genetic constraint (gnomAD): Loss-of-function variants: 59 observed, 42.64 expected, observed/expected ratio (o/e) 1.38, 90% interval 1.12 to 1.72. The synonymous counts are far from expectation, so gnomAD's model fits this gene poorly and the ratio says little. Missense variants: 666 observed, 489.13 expected, observed/expected ratio (o/e) 1.36, 90% interval 1.28 to 1.45. Synonymous variants: 246 observed, 185.64 expected, observed/expected ratio (o/e) 1.33, 90% interval 1.19 to 1.47.
Homologues: Orthologues: chimpanzee PSG4 (94% identical), chimpanzee PSG4 (92% identical). Paralogues in human: PSG7 (90% identical), PSG3 (89% identical), PSG8 (89% identical), PSG6 (89% identical), PSG1 (88% identical), PSG9 (85% identical), PSG5 (68% identical), PSG2 (66% identical), PSG11 (65% identical), CEACAM1 (41% identical), CEACAM5 (39% identical), CEACAM6 (37% identical), and 12 more.
Diseases named in the same sentence as PSG4 in open-access papers:
PSG4 is named in the same sentence as 10 diseases in open-access papers, as found by Europe PMC text mining. Sharing a sentence is not in itself a finding about the gene and the disease. The quoted sentences say what the papers report.
breast carcinoma (1 paper, 2023). "Six of these genes (MRPS30, SETD9, ADGRV1, ZNF703, PRR33, and PSG4) showed different directions of association with breast cancer in epithelial vs. stromal (nonepithelial) cells." (PMID 36690614, 2023). "Cell-type-specific TWAS using MiXcan identified five genes (ADGRV1, ZNF703, TMEM245, CDYL2, and PSG4), including three novel breast cancer susceptibility genes, that were not identified by either PrediXcan or PredictDB." (PMID 36690614, 2023). "Importantly, MiXcan uniquely identified three novel breast cancer susceptibility genes (ZNF703, TMEM245, and PSG4) that were not previously implicated by breast cancer GWAS11–13 nor TWAS14–16,32." (PMID 36690614, 2023).
dilatation (1 paper, 2021). "Of these, IGFBP-2, PSG4, and LXN levels in plasma were independent of cervical dilatation." (PMID 33857242, 2021).
endometriosis (1 paper, 2023). The growth of functional endometrial tissue in anatomic sites outside the uterine body. "Consensus clusters associated with genes for oxytocin receptor (OXTR) and pregnancy-specific beta-1-glycoprotein 4 (PSG4) also had lower expression in endometriosis cases in comparison with controls." (PMID 37443771, 2023).
nasopharyngeal carcinoma (1 paper, 2025). A carcinoma arising from the nasopharyngeal epithelium. "Furthermore, we found that the core genes of the nasopharyngeal carcinoma radiosensitivity signature (NPC-RSS), namely SMARCA2, DMC1, CD9, PSG4, and KNG1, had significant correlations with previously published genes related to radiosensitization." (PMID 40530955, 2025).
cancer (2 papers, 2020 to 2022). A tumor composed of atypical neoplastic, often pleomorphic cells that invade other tissues. "The RNAs with significantly higher expression levels in cancer tissues than in normal tissues include PELATON, INSL4, PSG1, PSG4." (PMID 35454778, 2022). "Specifically, pregnancy-specific glycoproteins, including PSG4, PSG5, and PSG7, were those proteins jointly interacting with CTD-2218G20.2 and cancer-related proteins, which were highly correlated with CTD-2218G20.2 (PCC > 0.3)." (PMID 32117443, 2020). "Specifically, CTD-2218G20.2 was predicted to interact with 86 proteins (Pearson correlation coefficient, PCC > 0.3), some of which, including PSG4, PSG5, and PSG7, could also interact with cancer-related proteins, including KISS1, TIMP2, MMP11, IGFBP1, EGFR, and CDKN1C." (PMID 32117443, 2020).
tumor (2 papers, 2016 to 2025). "Previous studies have demonstrated that the core genes of NPC-RSS, including SMARCA2, DMC1, CD9, PSG4, and KNG1, are associated with tumor radiosensitization to varying degrees." (PMID 40530955, 2025).
PSG4 also shares sentences with these, for which no sentence is quoted: atherosclerosis (1 paper); genetic diseases (1); Miscarriage (1); pregnancy (1).